IRS1 (insulin receptor substrate 1)
Diseases named in the same sentence as IRS1 in open-access papers (continued):
Sharing a sentence is not in itself a finding about the gene and the disease.
breast cancer (140 papers, 2006 to 2025). A primary or metastatic malignant neoplasm involving the breast. "More recently, IRS1 has also been implicated in progesterone receptor (PR)-driven stemness and endocrine resistance in ER+ breast cancer." (PMID 35846378, 2022). "The IRS1 (insulin receptor substrate 1) protein has a role in DNA repair and has been implicated in medulloblastoma, breast cancer, and osteosarcoma." (PMID 35460704, 2022). "IRS1 is closely related to the immune microenvironment and can affect CD4+ T cells and IFN-γ levels, and IRS1 was associated with resistance to multiple chemotherapeutic agents in breast cancer cells." (PMID 35387129, 2022). "IRS-1 has been associated with breast cancer progression with poor differentiation, cell survival, proliferation, and motility." (PMID 33991522, 2021). "TAZ deregulation in breast cancer causes IRS1 overexpression, which amplifies the insulin response and increases cell proliferation in a 3-dimensional Matrigel culture." (PMID 32722184, 2020). "In this regard, loss of IRS-1 expression increases mammary tumor metastasis in a mouse MMTV-PyMT tumor model." (PMID 31393907, 2019). "The hybrid PN analysis obtained in this study resulted to identify the increased expression of IGF-1R, IRS-1 and ER-α drastically involved in increased risk of breast cancer metastasis." (PMID 29787591, 2018). "In seeking to identify IRS-interacting proteins, we found that proteins related to RNA translation, such as poly(A) binding protein (PABP), and eukaryotic initiation factors (eIF) 4E and 4G, associate with IRS-1 in MCF-7 human breast cancer cells." (PMID 26074875, 2015). "Over-expression of IRS-1 has been associated with breast cancer, and estrogen has been shown to enhance transcription/translation of IRS-1." (PMID 22348058, 2012). "Of the genes examined, only genetic variants in IGF1R and its adaptor protein IRS1 were associated with risk of breast cancer in BRCA1 carriers." (PMID 19843326, 2009). "Both IGF1R overexpression and IRS1 overexpression have been associated with breast cancer development, and IGF1R is overexpressed in a majority of breast tumors." (PMID 19843326, 2009). "Mammary tumor metastasis is significantly diminished in PyV-MT:Irs-2-/- mice, and Irs-1 deficient tumors that express elevated levels of active (i.e. tyrosine phosphorylated) Irs-2 have enhanced metastatic rates." (PMID 19534786, 2009). "There is therefore a strong rationale for why genetic variation in IGF1R and IRS1 would be important in breast cancer risk in BRCA1 carriers." (PMID 19843326, 2009). "In breast cancer cells, IRS-1 overexpression has been associated with tumour development and hormone independence." (PMID 17043687, 2006). "In turn, IGF2 and IRS1 are significantly associated with poor prognosis in breast cancer patients." (PMID 38474285, 2024). "Variations in TNFα, PPARγ, and IRS-1 genes are associated with survival in breast cancer patients." (PMID 37886170, 2023). "PTEN downregulation was reported to activate PI3K/Akt pathway which may involve prolonged association between PIK3R1/p85α and the IRS-1 as well as with ErbB3, contributing to the therapy resistance in breast cancers." (PMID 31660072, 2019). "Increased IRS1 abundance has been associated with breast cancer cell proliferation." (PMID 29868002, 2018). "Moreover, overexpression of IRS1 has also been linked to anti‐oestrogen resistance and hormone independence in breast cancer." (PMID 28272775, 2017). "However, there was suggested modification by menopausal status for the rs1801278 polymorphism in the IRS1 gene (interaction p-value, pint = 0.06), which appeared to decrease the risk of premenopausal, while increasing the risk of postmenopausal breast cancers." (PMID 27376028, 2016). "Finally, IRS1 shows positive association with ER+ breast cancer in both data sets analysed here as well as in other studies." (PMID 22343619, 2012).
breast cancer (continued). "Immunoprecipitation and Western blot analysis were performed to examine whether IRS-1 associates with erbB receptors, notably erbB3, in the ER+ breast cancer cell lines." (PMID 21939528, 2011). "Furthermore, the crosstalk between ER and IRS-1 increases the risk of breast cancer." (PMID 37511200, 2023). "CDK12 has been implicated as a pro-tumorigenic factor in breast cancer, primarily due to its co-amplification with the HER2 oncogene and its synergistic interaction with oncogenic pathways such as WNT and IRS1-ErbB-PI3K signaling." (PMID 39806366, 2025). "In the MCF-7 breast cancer cell line, estradiol enhances the expression of the insulin receptor substrate-1 (IRS-1), activating insulin signaling." (PMID 38672654, 2024). "IRS1 has also been found to be downregulated and to play a key role in cell proliferation and survival in breast cancer." (PMID 38397596, 2024). "For instance, TRAF4 has been reported to mediate IRS1 ubiquitination, regulating IRS1 binding with IGF-1R and subsequent IRS1 phosphorylation, leading to the stimulation of proliferation in breast cancer cells." (PMID 38272982, 2024). "In breast cancer, IRS1 overexpression also promotes the growth and proliferation of BT 20 cells and induces the formation of larger tumors in vivo." (PMID 36975518, 2023). "IGF-1 binds to its cognate receptor to induce phosphorylation of IRS-1 and triggers a cascade of events that eventually results in breast cancer development, progression, and metastasis." (PMID 37511200, 2023). "Furthermore, siRNA knockdown of IRS1 or treatment with the IRS1 inhibitor NT-157 had a significant anti-proliferative effect in ERα Y537S cell lines, implicating IRS1 as a potential therapeutic target for restoring treatment sensitivity to patients with breast cancers harboring ERα Y537S mutations." (PMID 38036546, 2023). "Evidence of this is that cells expressing miR-30e abolish IRS1 in breast cancer cells, thereby suppressing breast cancer cell growth." (PMID 36831374, 2023). "The presence of IRS2 inhibited the ability of IRS1 to sensitize myeloblast-like and breast cancer cells to taxol, etoposide, and vincristine therapy and silencing of IRS2 potentiates the effects of ruxolitinib in myeloproliferative neoplasms cells." (PMID 35816477, 2022). "One example is the GR–IRS-1 (insulin receptor substrate 1) axis, which is essential for regulating breast cancer cell survival, invasion, and metastasis." (PMID 36661673, 2022). "IRS1 has been identified to be highly expressed in breast cancer, and regulates the sensitivity of breast cancer cells to chemotherapy." (PMID 34093789, 2021). "In summary, we discover a FOXO3a-miRNA negative feedback inhibition loop to control the IGF2/IGF-1R/IRS1 signaling in HER2-positive breast cancer cells sensitive to Herceptin." (PMID 33976188, 2021). "These miRNAs appeared to act as tumor suppressors by targeting Insulin-like Growth Factor 1 Receptor (IGF-1R) and Insulin Receptor Substrate 1 (IRS1), often overexpressed in breast cancer." (PMID 34298969, 2021). "miR-148a/152 overexpression is associated with marked inhibition of breast cancer cell proliferation and angiogenesis by targeting IGF-1R and IRS1 and consequently their downstream signaling pathway." (PMID 34778378, 2021). "In recent study, researchers found that IGF2/IGF-1R/IRS1 signaling conferred Herceptin resistance in HER2-positive breast cancer." (PMID 34837929, 2021). "Phospho-PR-B cooperates with IRS-1 to promote outgrowth of endocrine-resistant and stem-like breast cancer cells." (PMID 33144693, 2021). "Endocrine-resistant models of luminal B breast cancer induced p-PR in 3D cultures and required PR and IRS-1 for tumoursphere formation." (PMID 33144693, 2021). "IRS-1 silencing also promotes apoptosis and increases the sensibility to chemotherapy in estrogen receptor–positive breast cancer cells." (PMID 33991522, 2021).
breast cancer (continued). "We next examined the role of IRS1 in determining the efficacy of Herceptin against HER2-positive breast cancer in vivo." (PMID 33976188, 2021). "Our findings provide several insights into our understanding of the molecular basis of IGF2/IGF-1R/IRS1 signaling activation in Herceptin-resistant breast cancer." (PMID 33976188, 2021). "Taken together with our results implicating IRS-1 in the development of aggressive breast cancer phenotypes, IRS-1 is emerging as an attractive target as a key ER/PR-binding partner." (PMID 33144693, 2021). "Taken together, these data demonstrated a crucial role for miR-128-3p and miR-30a-5p transcriptionally regulated by FOXO3a in control of IRS1 expression in HER2-positive breast cancer cells." (PMID 33976188, 2021). "Overall, our studies have demonstrated that exosomes from breast cancer cells with a lower level of Ca2+ contain more miR-145, which targets IRS1 to exhibit an anti-angiogenic effect." (PMID 33414420, 2021). "Upregulation of IRS1 increases tumour proliferation and metastasis in many human malignancies, including PCa and breast cancer cells." (PMID 34366863, 2021). "Next, we found that reduction of several FOXO3a-driven miRNAs played a crucial role in upregulation of both IGF2 and IRS1 in Herceptin-resistant breast cancer cells." (PMID 33976188, 2021). "Insulin promotes the growth of breast cancer cells in nude mice, and increases the proliferation and migration of MCF-7 human breast cancer cell line by upregulating insulin receptor substrate 1 and activating the Ras/Raf/ERK pathway." (PMID 32631390, 2020). "Recently it has been reported that insulin receptor substrate 1 (IRS1) in breast cancer cells is a transcriptional target of TAZ." (PMID 32722184, 2020). "In MCF-7 human breast cancer cell line, estradiol has potentiating effects on insulin signaling via increasing the expression of the insulin receptor substrate-1 (IRS-1)." (PMID 32774370, 2020). "It has been reported that IRS-1 is highly expressed and active in a variety of tumors, including hepatocellular carcinomas (HCCs), breast cancers, pancreatic cancer, colon cancer, liposarcomas, leiomyomas and adrenal cortical carcinomas." (PMID 33109107, 2020). "They explained that IGF-I/-II normally binds to type I IGF receptor (IGF-IR), which mostly activates the adaptor protein insulin receptor substrate-1 (IRS-1), also found over-expressed in breast cancers." (PMID 32012980, 2020). "As we and others have reported in breast cancer, IRS-1 was expressed in both the cytoplasm and nuclei of ADC." (PMID 31393907, 2019). "Conversely, estrogen influences the IGF-1 pathway by increasing the expression of both IGF-1R and IRS1 in breast cancer cells." (PMID 30692633, 2019). "In metastatic mouse mammary tumors, total Irs-1 expression is equivalent to the level of expression observed in non-metastatic tumors, but serine phosphorylation is increased, which inhibits Irs-1 tyrosine phosphorylation and function." (PMID 31393907, 2019). "Studies showed that increased expression of estrogen by ligand binding interaction (IGFs with IGF-1R) can regulate the downstream signaling mediators such as IRS-1, Akt and PI3k in breast cancer cells." (PMID 29787591, 2018). "Estrogen also enhances the expression and tyrosine phosphorylation of IRS1 in a variety of breast cancer lines." (PMID 29868002, 2018). "So, it is important to note that IGF-1R, IRS-1 and ER-α serve as important inhibitory targets in breast cancer treatment." (PMID 29787591, 2018). "IRS1 expression sensitized MCF-7 cells to breast cancer chemotherapeutic agents, likely by affecting Annexin-2 cellular distribution." (PMID 29868002, 2018). "In breast cancer cells, transcriptional activity of IRS-1 can be increased by steroidal hormones such as estrogen and progesterone respectively in response to IGF-1." (PMID 29787591, 2018).
breast cancer (continued). "Two genes associated with pig melanoma (IRS1, NUAK1) were described as potential key players in human melanoma tumors and EPB41L4A-AS2 showed tumor suppressor features in breast cancer." (PMID 29963229, 2018). "In the un-treated model, proteins (ER-α, IGF-1R, Akt and IRS1) were shown to be over-expressed which leads towards breast cancer metastasis." (PMID 29787591, 2018). "We demonstrated that mTORC1 inhibition with RAD001 (everolimus) induces IGF-1R/InsR/IRS-1/IRS-2-dependent activation of PI3K/AKT signaling in ER+ breast cancer cells and human tumors treated ex vivo." (PMID 29507656, 2018). "We found that reducing IRS-1 levels in breast cancer cells resulted in a reduced expression of ER-α." (PMID 29787591, 2018). "Overexpression of miR-152 significantly inhibited cell proliferation, colony formation and tumor angiogenesis by targeting IGF-1R and IRS1 in breast cancer." (PMID 29162853, 2017). "Taken together, our study indicated that IRS1 was a direct downstream target of miR-30e and was involved in the miR-30e-induced suppression of the activity of cell migration and invasion in breast cancer cell." (PMID 29162879, 2017). "The Late IRS-1 signature was most significantly over-represented across the subtypes and as a result, its prognostic value was determined in breast cancer tumors." (PMID 26991655, 2016). "IRS-null breast cancer cells (T47D-YA) were engineered to express IRS-1 or IRS-2 alone and their ability to mediate IGF ligand-induced proliferation, motility, and gene expression determined." (PMID 26991655, 2016). "IRS-1 has been found to directly bind to ERα and co-transfer to the nuclei of breast cancer cells, indicating a interaction between IRS-1 and ERα in controlling breast cancer development." (PMID 26795955, 2016). "We examined the associations of 22 polymorphisms across five IGF1 pathway genes (IGF1, IGFBP3, IGF1R, IRS1, and PI3KCB) with risk of breast cancer among women of European and East Asian descent." (PMID 27376028, 2016). "Substantiating this, overexpression or knockdown of IRS1 or IRS2 in MMTV-ErbB2 mammary cancer cell lines had little effect upon ErbB2 signaling." (PMID 27765041, 2016). "Elevated expression of IGF-IR or IRS-1 appears to increase drug and radio resistance of breast cancer cells and favor cancer recurrence in patients." (PMID 26236690, 2015). "MiR-126-3p was also reported to suppress breast cancer cell growth by targeting insulin receptor substrate-1 (IRS-1), and inhibit proliferation of small cell lung cancer cells by targeting SLC7A5." (PMID 26244545, 2015). "Exceptionally, downregulation of IRS-1 is found in advanced breast cancer and non-small cell lung cancer." (PMID 26074875, 2015). "The data presented in this manuscript suggests an interaction between the two pathways, as demonstrated by the enhanced protein levels of IGF-1R, p-IGF-1R, p-IRS-1, p-AKT and p-S6 in ovarian and breast cancer cells having loss-of-function mutations of BRCA1." (PMID 26510816, 2015). "While miR-126 has been shown previously to directly regulate IRS-1 translation in hepatocytes and in HEK293 and MCF7 breast cancer cells, we have shown for the first time that IRS-1 is a potential target of miR-126 in adipose tissue." (PMID 24749062, 2014). "IRS-1, a docking protein, is highly expressed in many kinds of cancers where it acts as an oncogene, e.g., pancreatic cancer and breast cancer; we found that IRS-1 is mainly expressed in the cytoplasm of the CRC cell line HCT-116." (PMID 24312276, 2013). "We recently demonstrated that human protein tyrosine phosphatase (PTP) L1, a large cytoplasmic phosphatase also known as PTP-BAS/PTPN13/PTP-1E, is a negativeregulator of IGF-1R/IRS-1/Akt path-way in breast cancer cells." (PMID 23514123, 2013). "For instance, IGF1R and IRS1 were identified as predictive markers of tamoxifen response in patients with early breast cancer." (PMID 22343619, 2012).
breast cancer (continued). "Previous studies showed that IRS1 was down-regulated in non-small cell lung tumors and poorly differentiated, ER(-) breast carcinoma." (PMID 23112878, 2012). "Recently, we reported that IRS-1 can interact with EGFR, resulting in loss of recruitment of IRS-1 by IGF-IR and reducing signalling via this receptor in an ER+, tamoxifen-resistant MCF-7 breast cancer cell line." (PMID 21939528, 2011). "The increase in HRGβ1-induced Akt phosphorylation observed following treatment of MCF-7 and T47D breast cancer cells with the IGF-IR/IR inhibitor ABDP for 24 hours was effectively blocked using siRNA specific to IRS-1." (PMID 21939528, 2011). "In this study we report that α-TEA functions as an IRS-1 suppressor in human breast cancer cells via JNK-dependent phosphorylation of IRS-1 at ser-307." (PMID 21119656, 2011). "An inhibitory effect of JNK on IRS-1 activity via phosphorylation at ser-307 in human breast cancer cells has also been reported in Taxol treatments." (PMID 21119656, 2011). "In contrast, Irs-1-/- mammary tumor cells derived from mouse mammary tumor virus (MMTV)-polyoma virus middle T antigen (PyV-MT) mice are more resistant to apoptosis in response to serum deprivation than wildtype cells." (PMID 19534786, 2009). "Specifically, PyV-MT:Irs-1-/- mammary tumors have a greater incidence and rate of lung metastasis when compared with PyV-MT:WT tumors." (PMID 19534786, 2009). "Akt and mTor activation were enhanced significantly in Irs1-/- mammary tumors when compared with the level of activation in wildtype tumors." (PMID 19534786, 2009). "An alternative mechanism for the differential involvement of IRS-1 and IRS-2 in cancer that would allow for the activation of a common signaling pathway by these adaptor proteins was revealed during the analysis of Irs1-/- mammary tumors." (PMID 19534786, 2009). "In metastatic mouse mammary tumors, Irs-1 is phosphorylated on serine residues in the PI3K binding region and the association with p85 is decreased when compared with non-metastatic tumors." (PMID 19534786, 2009). "IRS-1 is the predominant IRS family member that is activated by IGF-1 in well-differentiated estrogen receptor positive (ER+) human breast carcinoma cell lines." (PMID 19534786, 2009). "Studies in breast carcinoma cells reveal interactions between IRS-1 and the transcription factors β-catenin, ER-α and the androgen receptor (AR)." (PMID 19534786, 2009). "Estrogen upregulates IRS-1 in ER+ breast carcinoma cells and IRS-1 expression decreases in response to the ER antagonists tamoxifen and ICI 182,780." (PMID 19534786, 2009). "Insulin receptor substrate-1 is the predominant signalling molecule activated in MCF-7 breast cancer cells in response to IGF-I stimulation and this activation is required for IGF-I-stimulated cell proliferation of these cells." (PMID 17043687, 2006). "Overall, the striking effect of inhibition of IRS1 via NT-157, alone or in combination with lasofoxifene or fulvestrant, may offer a treatment avenue for ET-resistant breast cancers." (PMID 38036546, 2023). "Through the random walk method, we finally identified that GGTLC1, PRC1, and IRS1 may have produced breast cancer drug-resistant phenotypes through immune-mediated pathways." (PMID 35387129, 2022). "Through functional enrichment analysis, immune microenvironment analysis, and other computational analysis methods, we identified PRC1, GGTLC1, and IRS1 as genes that may mediate breast cancer chemoresistance through the immune pathway." (PMID 35387129, 2022). "Our computational analysis found that increased expression of IRS1 may lead to breast cancer resistance, which is inconsistent with the results of previous cell experiments." (PMID 35387129, 2022).